LAMP2 (lysosome associated membrane protein 2)
Diseases named in the same sentence as LAMP2 in open-access papers (continued):
Sharing a sentence is not in itself a finding about the gene and the disease.
cone-rod dystrophy (2 papers, 2012 to 2013). Inherited retinal dystrophies that belong to the group of pigmentary retinopathies. "Here, we present the results of a comprehensive ophthalmologic examination in a small Danon family with cone-rod dystrophy (CRD) due to an uncommon missense mutation in LAMP2." (PMID 22290069, 2012). "A recent publication also described a cone-rod dystrophy, characterized by loss of photoreceptor and RPE cells, in a patient carrying a LAMP2 mutation." (PMID 24066113, 2013).
coronary artery disease (2 papers, 2022 to 2023). "Patients with coronary artery disease showed an upregulation of LAMP2 expression in peripheral blood mononuclear cells when compared with the control group." (PMID 38275601, 2023). "The collected data revealed a role for LAMP2 in lipid homeostasis and coronary artery disease development." (PMID 38275601, 2023). "According to the literature, compared to healthy controls, LAMP-2 gene expression and protein levels in peripheral blood leukocytes of patients with coronary heart disease are significantly increased." (PMID 36358920, 2022).
dementia (2 papers, 2014 to 2022). Loss of intellectual abilities interfering with an individual's social and occupational functions. "There are indications that CSF P-tau181P can be used to differentiate AD from other dementias, and it will be interesting to investigate whether LAMP-2 can be similarly used as a more specific marker for AD." (PMID 24101586, 2014).
familial cardiomyopathy (2 papers, 2017 to 2023). An instance of cardiomyopathy that is caused by an inherited modification of the individual's genome. "Three different guide RNAs for human gene Desmin and four for human gene LAMP2, which are mutated genes in the hereditary cardiomyopathy, were designed with web-based software ZiFiT Targeter." (PMID 29212218, 2017).
gastric adenocarcinoma (2 papers, 2014 to 2020). "In the present study, the lysosomal protein expression was similar to the patterns observed for LC3-II formation, including the induction of Lamp2 and cathepsin B in patients with low grade differentiated gastric adenocarcinoma." (PMID 24527069, 2014). "In light of the key role of lysosome signaling in autophagy and apoptosis, the alternations in autophagy-lysosome progression were studied next, based on measurements of Lamp2 and cathepsin B levels in human gastric adenocarcinoma." (PMID 24527069, 2014). "Significant elevation of cathepsin B and Lamp2 levels in human gastric adenocarcinoma was found." (PMID 24527069, 2014). "In the present study, protein analysis of human gastric adenocarcinoma revealed significant upregulation of autophagy regulatory proteins, LC3, cathepsin B and Lamp2." (PMID 24527069, 2014).
Hyperammonemia (2 papers, 2023 to 2026). An increased concentration of ammonia in the blood. "We found that hyperammonemia induces lysosomal dysfunction, with reduced LysoTracker staining and cathepsin L levels and increased LAMP2 content." (PMID 41601700, 2026).
infertile (2 papers, 2018 to 2021). "In fact, we observed that Lamp2y/− rats mostly died after 60 days and were infertile, but Lamp2 deficient heterozygotes were mostly normal." (PMID 29720683, 2018).
ischemic stroke (2 papers, 2024). A stroke disorder caused by obstruction of blood flow to the brain, due to thrombotic (local blood clot formation) or embolic (due to a blood clot or other material traveling from another site) event. "miR-487b-5p directly targets LAMP2, affecting autophagy in cortical neurons, and miR-207 and miR-352 can affect autophagy by directly targeting LAMP2 in ischemic stroke." (PMID 38338839, 2024). "Thus, simvastatin can enhance neuronal autophagic activity following ischemic stroke by regulating the p-AMPK/LC3B/LAMP2 axis, ultimately promoting neuronal survival." (PMID 39707228, 2024). "Additionally, this study demonstrated that simvastatin administration promoted the formation of autophagic lysosomes after ischemic stroke, evidenced by a significant increase in the co-localization of LC3B with lysosome-associated membrane protein 2 (LAMP2) and LC3B with cathepsin B." (PMID 39707228, 2024).
liver cancer (2 papers, 2020 to 2023). An epithelial or non-epithelial malignant neoplasm that arises from the liver. "LAMP2 has been shown to play roles in many diseases, but few such studies have been performed in liver cancer." (PMID 32295144, 2020). "Zheng’s study found that LAMP2 expression was significantly reduced in liver cancer and was correlated with metastasis, serum alpha-fetoprotein levels, vascular invasion, recurrence, and poor prognosis of liver cancer." (PMID 37986192, 2023). "This might be attributed to LAMP2 associated epithelial-mesenchymal transition (EMT), as LAMP2 could inhibit the expression of Snail, upregulate E-cadherin, and inhibit EMT of liver cancer cells." (PMID 37986192, 2023).
meningioma (2 papers, 2020). A generally slow growing tumor attached to the dura mater. "Thus, subject to further investigation, discordantly expressed transcripts/proteins such as HTRA1 and LAMP2 could hold promise as diagnostic blood biomarkers for high-grade meningioma." (PMID 33167358, 2020). "The corresponding transcript levels were validated for PACS1, LAMP2, HTRA1 and CST3 in meningioma tissue." (PMID 33167358, 2020). "Unlike HTRA1, LAMP2 has remained unreported in meningioma until now." (PMID 33167358, 2020). "Following RT-qPCR, we identified a significant reduction in relative expression for CST3, LAMP2, PACS1 and HTRA1 in grade III meningioma compared with grade I compatible with our hypothesis that increased abundance of these proteins in the tumour originates from the blood circulation." (PMID 33167358, 2020). "Notably, we derived a plasma signature of 21 discordantly expressed genes showing positive changes in protein but negative in transcript levels of high-grade meningiomas, including the validated genes CST3, LAMP2, PACS1 and HTRA1, suggesting the acquisition of these proteins by tumour from plasma." (PMID 33167358, 2020).
mucolipidosis IV (2 papers, 2020). "Similarly, defects in lysosomal membrane proteins such as NPC1, LAMP2 and MCOLN1 cause Niemann-Pick type C (NPC), Danon and Mucolipidosis type IV (MLIV) diseases, respectively." (PMID 32375321, 2020).
myelodysplastic syndrome (2 papers, 2023). A clonal hematopoietic disorder characterized by dysplasia and ineffective hematopoiesis in one or more of the hematopoietic cell lines. "Myelodysplastic syndrome (MDS) AML patients exhibit resistance to azacytidine and poor survival as a result of a significant defect in CMA caused by a lack of LAMP2 expression, and lysosomal autophagy inhibitors such as CQ can be effective on AML cells lacking LAMP2." (PMID 37180758, 2023).
myocardial infarction (2 papers, 2022 to 2023). Gross necrosis of the myocardium, as a result of interruption of the blood supply to the area, as in coronary thrombosis. "Transfection with ad‐LAMP2 mitigated the area of myocardial infarction from 57% to 31%, and co‐transfection with Ad‐LAMP2 and Ad‐ATG5 gained more protection to approximately 21%." (PMID 36562207, 2023). "The expression of ACSL4, LAMP2, PTEN, PTGS2, and SAT1 were different in the early and late stages of myocardial infarction." (PMID 36407421, 2022). "Analysis of human blood sample sequencing datasets and mouse myocardial infarction sequencing datasets as well as cardiomyocyte hypoxia experiments indicated that FRGs ALOX5, CAMKK2, KDM6B, LAMP2, PTEN, PTGS2, and ULK1 may be potential biomarkers of AMI." (PMID 36407421, 2022).
Niemann-Pick disease, type C1 (2 papers, 2008 to 2020). Type C Niemann-Pick disease associated with a mutation in the gene NPC1, encoding Niemann-Pick C1 protein. "Reassuringly, known late endosome specific proteins such as the small GTPase Rab7, the lysosomal glycoprotein LAMP2, or the NPC1 protein involved in Niemann Pick type C disease were found." (PMID 18648502, 2008).
osteosarcoma (2 papers, 2020 to 2022). A usually aggressive malignant bone-forming mesenchymal neoplasm, predominantly affecting adolescents and young adults. "We constructed a fusion expression vector of RGD and LAMP2, and LAMP2 carried the integrin-targeting RGD peptide to exosome membrane surface, allowing exosomes to target osteosarcoma cells with high integrin expression." (PMID 35459258, 2022).
Pick disease (2 papers, 2019 to 2023). A rare neurodegenerative disorder leading to dementia. "The only exceptions to this trend were lower levels of LAMP-2 in patients with Pick’s disease than patients with FTD-GRN (which still trended higher than controls), and the lack of accumulation of low molecular weight GCase in patients with FTLD-TDP type C." (PMID 37118844, 2023). "Patients with sporadic FTLD-TDP types A and C and FTLD-tau (Pick’s disease) exhibited similar increases in CatD activity, LAMP-1 and LAMP-2 levels, and lysosomal storage material as patients with FTD-GRN." (PMID 37118844, 2023).
Pleural effusion (2 papers, 2011 to 2014). The presence of an excessive amount of fluid in the pleural cavity. "Another sample source for potential biomarker candidates is pleural effusion, where Niemann-Pick disease type C2 protein (NPC2), periostin, multimerin 2, CD166, and lysosome-associated membrane glycoprotein-2 (LAMP-2) were differentially expressed." (PMID 24550697, 2014).
polyarteritis nodosa (2 papers, 2022 to 2024). Polyarteritis nodosa (PAN) is a rare, clinically heterogeneous, rheumatologic disease characterized by necrotizing inflammatory lesions affecting small- and medium-sized blood vessels. "The value of LAMP-2-ANCA seropositivity as a biomarker may be greatest among AAV patients who have MPO/PR3-ANCA-negative SVV, but more so in individuals with middle vessel vasculitis (MVV), namely, polyarteritis nodosa (PAN) and large vessel vasculitis (LVV), namely Takayasu’s arteritis (TAK)." (PMID 38612581, 2024). "Furthermore, serum anti-LAMP-2 antibody levels have not been evaluated in VAS-HTN, particularly in Takayasu arteritis (TA) and polyarteritis nodosa (PAN)." (PMID 35356030, 2022).
prediabetes (2 papers, 2017 to 2020). "Examination of the classical autophagy markers, LC3II and LAMP2, revealed a remarkable rise in LC3-II and LAMP-2 mRNA expression in subjects with prediabetes, while patients with NDT2DM and ADT2DM showed the significant reduction in both LC3II and LAMP2 mRNA and protein expression." (PMID 33041786, 2020).
sarcoidosis (2 papers, 2017 to 2019). Sarcoidosis is a multisystemic disorder of unknown cause characterized by the formation of immune granulomas in involved organs. "In sarcoidosis we observed upregulation of LAMP2 both at the gene and protein level." (PMID 30946009, 2019). "Surprisingly, we found that CHQ inhibits the increased levels of LAMP2, HIF-α isoforms, and cytokine production in sarcoidosis." (PMID 30946009, 2019). "The relative gene expression levels for ATP6AP1, CYBB, LAMP2, and SERPINA1 were significantly higher in sarcoidosis monocytes as compared to healthy monocytes." (PMID 28577019, 2017). "We hypothesized that CHQ modulates LAMP2, HIF-1α, and HIF-2α levels and cytokine production in sarcoidosis AMs and PBMCs." (PMID 30946009, 2019). "Interestingly, CHQ decreased LAMP2 levels and both HIF-1α (by approximately 50%) and HIF-2α protein expression (by approximately 65%) in sarcoidosis AMs after LPS stimulation." (PMID 30946009, 2019).
Tauopathies (2 papers, 2015 to 2025). "Our results reveal the association of retromer complex component vacuolar protein sorting-associated protein 35 (VPS35) and lysosome-associated membrane glycoprotein 2 (LAMP2) with specific types of phospho-tau lesions in tauopathies." (PMID 40082954, 2025). "The analysis of phospho-tau associated proteomes revealed major sequestration of lysosomal proteins in tau aggregates in all the studied tauopathies, including multiple V-type proton ATPase subunits and the LAMP2." (PMID 40082954, 2025). "Among the phospho-tau associated proteins shared across tauopathies, we selected VPS35 and lysosome-associated membrane protein (LAMP2) for further studies." (PMID 40082954, 2025). "Of note, we also found that LAMP2 co-localizes with AT8 phospho-tau in a variety of phospho-tau lesions across tauopathies, most notably in AD TANCs, CBD and PSP CBs, and both glial and neuronal aggregates in PiD." (PMID 40082954, 2025). "Neuropathologic characterization of VPS35 and LAMP2 corroborates the mass spectrometry proteomics findings, confirming their association with AT8-positive aggregates in all four major tauopathies." (PMID 40082954, 2025). "LAMP2 was selected for further examination across human tauopathies because the association of tau with LAMP2 has not been reported in previous studies of tau interactomes." (PMID 40082954, 2025).
triple-negative breast carcinoma (2 papers, 2022 to 2024). An invasive breast carcinoma which is negative for expression of estrogen receptor (ER), progesterone receptor (PR), and human epidermal growth factor receptor 2 (HER2). "To determine the trafficking pathway followed by ECM components, we measured Matrigel colocalisation with an early endosomal marker, EEA1, and a late endosomal/lysosomal marker, LAMP2, in MDA-MB-231 triple-negative breast cancer cells." (PMID 39666682, 2024).
alcoholic pancreatitis (1 paper, 2020). Acute or chronic inflammation of the pancreas due to excessive alcohol drinking. "Furthermore, immunoblotting analysis also revealed decreased levels of pancreatic LAMP1 and LAMP2 proteins in alcoholic pancreatitis patients compared with normal healthy control donors." (PMID 31987928, 2020).
aneurysm (1 paper, 2019). Bulging or ballooning in an area of an artery secondary to arterial wall weakening. "VSMCs, myofibroblasts, and fibroblasts acquired phagocytic markers LAMP2 and CD68 proportionally to the severity of aortic disease, and cells from dissecting aneurysms were positive for Ter-119, suggesting an association with red blood cells." (PMID 30943775, 2019).
aortic valve calcification (1 paper, 2021). "Recently, it was suggested that LAMP2 was involved in surface expression of RANKL of osteoblast, thus participating in osteoclastogenesis, a process found in aortic valve calcification." (PMID 34357353, 2021).
Azoospermia (1 paper, 2022). Absence of any measurable level of sperm,whereby spermatozoa cannot be observed even after centrifugation of the semen pellet. "Recent studies have found that LAMP2 was highly expressed in human spermatogonia, and some autophagy-related genes were dysregulated in the testicular germ cells of patients with non-obstructive azoospermia (NOA), suggesting that autophagy is related to male infertility." (PMID 35908066, 2022).
Barrett esophagus (1 paper, 2022). Esophageal lesion lined with columnar metaplastic epithelium which is flat or villiform. "Moreover, we found that LAMP2 expression was significantly associated with poor DSS in ESCA patients >60 years of age or without Barrett’s esophagus or a distal tumor central location." (PMID 35530327, 2022). "The correlations between LAMP2 expression and various clinicopathological features highlight the need to pay more attention to patients over the age of 60 and those without Barrett’s esophagus or distal tumor central location in order to improve their clinical outcomes." (PMID 35530327, 2022). "These correlations of LAMP2 expression with various clinicopathological features highlight that more attention should be paid to the patients with certain concomitant clinical traits, such as an age over 60 years, the absence of Barrett’s esophagus, or distal central location of the tumor." (PMID 35530327, 2022).
brain aneurysm (1 paper, 2024). A congenital or acquired aneurysm within the cranium. "These include Cer accumulation, LAMP-2 and NT up-regulation, brain aneurysms, mitochondrial damage (cerebral cortex, heart, kidney, liver), cellular infiltrates (heart, liver, kidney), increased Bowman’s space, interstitial hemorrhage between proximal tubules (kidney), and dilated rough ER (liver)." (PMID 38892068, 2024).
brain trauma (1 paper, 2023). "Previous research has indicated that lysosomal membrane injury leads to the suppression of autophagy and neurodegeneration following brain trauma, as well as to increases in LAMP2 levels in the injured brain section." (PMID 37174963, 2023).
calcium oxalate kidney stones (1 paper, 2024). "Since it may be a therapeutic target for ferroptosis in calcium oxalate kidney stones, we plan to conduct some experiments to overexpress LAMP2 and MDM4 genes in HK-2 cells to determine the effects of these genes on the cellular response to ferroptosis." (PMID 38536018, 2024).
Cardiac ischemia (1 paper, 2020). "Cardiac ischemia/reperfusion injury causes a decrease in Lamp2 and a consequent blockade of autophagic flux." (PMID 32117965, 2020).
cholestasis (1 paper, 2022). Impairment of the bile flow caused by obstruction within the liver, or outside the liver in the bile duct system. "First, to verify and further define cholestasis-dependent changes in autophagy proteins in our PSC samples, expression of p62, Beclin1, LC3a/b, ATG5/12, ATG7, LAMP1 and LAMP2 was evaluated by Western blotting using lysates prepared from PSC liver tissue." (PMID 36378690, 2022).
choriocarcinoma (1 paper, 2025). An aggressive malignant tumor arising from trophoblastic cells. "Previous studies have demonstrated that lysosomal membrane protein LAMP2, glycosylated by MGAT5, promotes choriocarcinoma progression by enhancing N-glycan–mediated cell adhesion through galectin interactions." (PMID 41061966, 2025).
chronic lymphocytic (1 paper, 2025). "Dilated transformation in patients with ALPK3 and LAMP2 variants occurred against a background of histologically verified (Dallas criteria) chronic lymphocytic, virus-negative myocarditis (per endomyocardial biopsy or explanted heart specimens)." (PMID 41440877, 2025).
chronic myeloid leukemia (1 paper, 2025). "This study revealed deregulation of asymmetric stem cell division markers during chronic myeloid leukemia (CML) progression, with pronounced downregulation of five key genes—CD63, SELL, NUMB, HK2, and LAMP2—during blast crisis compared to the chronic phase." (PMID 40868343, 2025).
chronic pancreatitis (1 paper, 2025). A chronic inflammatory process causing damage and fibrosis of the pancreatic parenchyma. "For instance, the expression of lysosomal membrane protein LAMP2, essential for autophagosome-lysosome fusion, is required for acinar cell homeostasis in mice, with deficiency resulting in unstimulated digestive enzyme release, a predisposing factor for acute and chronic pancreatitis." (PMID 41312553, 2025).
Cirrhosis (1 paper, 2015). A chronic disorder of the liver in which liver tissue becomes scarred and is partially replaced by regenerative nodules and fibrotic tissue resulting in loss of liver function. "We also divided patients as control into three clinical groups with different cirrhosis stages, hepatitis without cirrhosis, compensated cirrhosis and decompensated cirrhosis, to evaluate the effect of cirrhosis stage on baseline serum LAMP-2." (PMID 25894308, 2015).
Cohen syndrome (1 paper, 2016). Cohen syndrome (CS) is a rare genetic developmental disorder characterized by microcephaly, characteristic facial features, hypotonia, non-progressive intellectual deficit, myopia and retinal dystrophy, neutropenia and truncal obesity. "They propose to analyze the highly glycosylated protein intercellular cell adhesion molecule 1 (ICAM-1) and lysosome-associated membrane protein 2 (LAMP-2) in blood cells as a pre-screening test for Cohen syndrome." (PMID 26739145, 2016).